CD4 (CD4 molecule)
Diseases named in the same sentence as CD4 in open-access papers (continued):
Sharing a sentence is not in itself a finding about the gene and the disease.
pneumonitis (22 papers, 2007 to 2025). An inflammatory process affecting the lung parenchyma. "This hypothesis is consistent with previous description of checkpoint inhibitors pneumonitis (CIP) being associated with high frequency of BAL central memory CD4 T cells." (PMID 36605194, 2022). "The increase in the frequency of ICOS+CD4+ T cells in the blood was characteristic not only of patients with pneumonitis but also of those with hematological and skin irAEs." (PMID 40198121, 2025). "First, a significantly higher proportion of central memory CD4+ T cells (Tcms, CD4+CD45RA−CD62L+) were observed in the ICI-pneumonitis samples." (PMID 36944820, 2023). "Our data demonstrated that HS diet enhanced pneumonitis and enhanced inflammatory cytokine (IFNγ and IL-1β) expression in CD4+T cells in sites distal to tumor such as lung and also peripheral circulation." (PMID 35741331, 2022). "The major immunopathological phenomenon observed in sialadenitis and pneumonitis is infiltration of mononuclear cells, especially CD4+ T cells." (PMID 17284325, 2007). "Likewise, an effective antiviral immune response driven by IFN-γ-secreting CD4+ and CD8+ effector and memory T cells is essential for limiting viral spread in the airways and reducing the risk of bronchiolitis and pneumonitis." (PMID 40143221, 2025). "As T lymphocyte classes, cytotoxic CD8+, helper CD4 + and γδ+, differ in principal immune function, the specific lymphocytes triggered by injured tissue have been proposed both to augment or to reduce radiation-induced pneumonitis and fibrosis." (PMID 41261392, 2025). "Because the current cohort was small, unlike in the Spearman’s rank correlation coefficient analysis, neither the change in ICOS+CD4+ T cells nor in CXCL13 was identified as an independent risk factor for irAEs (or pneumonitis) in the multivariate analysis." (PMID 40198121, 2025). "In another study, NSCLC patients with ICI-pneumonitis showed an increased percentage of BAL central memory T cells and inflammatory TNF-αhi, IFN-γhi CD8+ T cells and decreased number of PD-1hi/CTLA-4hi CD4+ Treg, compared to non-pneumonitis ICI-treated control." (PMID 39247203, 2024). "Furthermore, in one case of ICI-related pneumonitis, binding of therapeutic antibody was stronger on lung CD4+ T cell than in blood." (PMID 36605194, 2022). "In MTX-induced pneumonitis, CD4+ cells may also be preferentially increased; this increase has also been demonstrated with the use of ampicillin, nitrofurantoin, and sirolimus." (PMID 22651223, 2012). "Therefore, MRL/lpr mice that had undergone transfer of CCR2-Treg cells showed significant amelioration of pneumonitis and sialadenitis progression in comparison with CD4+CD25- CCR2-transferred MRL/lpr mice." (PMID 17284325, 2007). "Although the role of a low-salt diet in clinical cancer patients is unknown, our data suggest that a low-salt diet, through the downregulation of NFAT5-mediated inflammasome complex, reduces pneumonitis and systemic circulating frequency pro-inflammatory CD4+T cells." (PMID 35741331, 2022). "In bone-marrow-transplantation models, latent MHV-68 infection leads to chronic and persistent pneumonitis and fibrosis, which is associated with the accumulation of macrophages and the influx of neutrophils and lymphocytes into the lung, with the latter being dominated by CD8 and CD4 T cells." (PMID 26138704, 2015). "CD4+CD25+Foxp3+ T cells (Treg cells) and CD4+CD25+Foxp3+ CCR2-transfected T cells (CCR2-Treg cells) were transferred via retro-orbital injection into 12-week-old MRL/lpr mice at the early stage of pneumonitis and sialadenitis, and the pathological changes were evaluated." (PMID 17284325, 2007). "The results showed that the absolute densities of IFN-γ-producing and/or IL-17-producing T cells were greater in ICI-pneumonitis patients than in controls, especially IFN-γ+ IL-17+ CD4+ T cells (i.e. functional definition of Th17.1 cells)." (PMID 36944820, 2023).
pneumonitis (continued). "Then, we characterized the CCR2-expressing CD4+CD25+ regulatory T cells and their therapeutic effect on sialadenitis and pneumonitis by accumulating them in target organs in MRL/lpr mice." (PMID 17284325, 2007). "The development of pneumonitis in MRL/lpr mice is characterized by the accumulation of T cells, especially CD4-CD8-B220+ and CD4+ T cells." (PMID 17284325, 2007). "An increased frequency of ICOS+CD4+ T cells was a better predictor for pneumonitis development than those of CXCL13 or IL-6 levels, and combined assessment of both changes in ICOS+CD4+ T cells and CXCL13 levels had an even greater predictive value for later development of pneumonitis." (PMID 40198121, 2025). "In a study of 18 ICI-treated patients, of whom 12 developed ICI pneumonitis, the ratio of CD4 + to CD8 + T-lymphocytes was not different in those with and without ICIP, but ICIP was associated with an increase in BAL absolute lymphocyte percentages." (PMID 40529125, 2025). "On the basis of these results, we investigated whether pneumonitis and sialadenitis in MRL/lpr mice could be ameliorated by accumulation of CCR2-expressing CD4+CD25+ regulatory T cells in target organs." (PMID 17284325, 2007). "Evaluation of T cell functionality revealed enhancement in the number of IFNγ- and IL-17-producing CD4+ T cells in the ICI group, compared with the control group, suggesting a unique contribution of these cells to the development and progression of ICI-pneumonitis." (PMID 39247203, 2024). "After transfer of CD4+ T cells from scurfy mice, but not of WT CD4+ cells or PBS, T cell-deficient B6/nude mice developed severe pneumonitis (seven of seven, 100%) and skin disease (seven of seven, 100%) resembling the disease spontaneously occurring in scurfy mice." (PMID 25890083, 2015). "While the proportions of both CD4+ T cells and CD8+ T cells were not altered by the therapy, the expression of ICOS in peripheral CD4+ T cells was significantly upregulated in patients with the irAE pneumonitis, but not in those without any irAEs." (PMID 40198121, 2025).
pulmonary hypertension (22 papers, 2009 to 2025). Increased pressure within the pulmonary circulation due to lung or heart disorder. "Our results show a consistent association between high viral load, low CD4 cell count, and both the risk of reaching clinical pulmonary hypertension thresholds and PASP progression of more than 10 mm Hg." (PMID 34296203, 2021). "We further categorised veterans with HIV by CD4 count or HIV viral load to assess the association between pulmonary hypertension risk and HIV severity." (PMID 34296203, 2021). "Other studies have showed that elevated levels of ADMA are associated with higher viral loads, lower CD4+ counts, and high risk of pulmonary artery hypertension in HIV patients." (PMID 34640478, 2021). "For instance, animals that lack T cells are more susceptible to severe pulmonary hypertension, which is attenuated by immune reconstitution with spleen cells, more specifically, CD4+ T cells." (PMID 32257910, 2019). "Finally, we observed that low CD4 count and high viral load were associated with an increased risk of pulmonary hypertension." (PMID 34296203, 2021). "One study has demonstrated downregulated IL-7R expression on CD4 T cells in scleroderma patients with pulmonary hypertension, which is consistent with our results." (PMID 35663995, 2022). "When modelling CD4 cell count and HIV viral load as time-varying covariates, the associations between viral control and risk of pulmonary hypertension became more pronounced." (PMID 34296203, 2021). "Low CD4 cell count and high HIV viral load contribute to increased pulmonary hypertension risk among veterans with HIV." (PMID 34296203, 2021). "An increase in circulating CD8 + effector T cells and elevation in CD4 + FOXP3 + (Treg) cells in patients with PAH have been corroborated in genetic models of pulmonary hypertension." (PMID 30081463, 2018). "Two recent studies found that CD4 count was independently associated with survival in 154 patients with HIV and PAH, with pulmonary hypertension as the direct cause of death in 72% of those affected." (PMID 23782480, 2013). "Epigenetic alterations which could potentially be used as biomarkers were also described for other cardiovascular diseases, e.g., methylated DNA of CD4 + cells in pulmonary arterial hypertension or DNA methylation profile of human leukocyte antigen-G in CAD." (PMID 37697352, 2023). "On the contrary, lower proportions of resting memory CD4 T cells, regulatory T cells (Tregs), activated NK cells, M0 macrophages, M1 macrophages and M2 macrophages, and resting mast cells were observed in the samples from patients with pulmonary hypertension, compared to the normal samples." (PMID 36246557, 2022). "Veterans with HIV who had a CD4 count lower than 200 cells per μL or of 200–499 cells per μL had a higher risk of pulmonary hypertension than did veterans without HIV (HR 1·94 [1·49–2·54], p<0·0001, for those with <200 cell μL and HR 1·29 [1·08–1·53], p=0·0048, for those with 200–499 cells per μL)." (PMID 34296203, 2021).
bronchiectasis (21 papers, 2007 to 2025). Segmental, irreversible dilation of the bronchial tree resulting in the accumulation of secretions which leads to obstruction. "Higher CD4 count was associated with a decreased risk of bronchiectasis (OR = 0.62; 95%-CI = 0.40–0.96)." (PMID 35015197, 2022). "Low pre-treatment IgG concentration, low IgA concentration, and low CD4 + T cell counts are factors known to be associated with bronchiectasis in CVID." (PMID 35015197, 2022). "The increased levels of cytokines CD4 lymphocytes in the BAL fluid suggest the possible causative mechanism in the lung in sulfur mustard gas-induced bronchiectasis by the recruitment of neutrophils into the lung." (PMID 17224076, 2007). "Elevated levels of CD4+ cells have been associated with systemic conditions like rheumatoid arthritis, Sjogren syndrome and ulcerative colitis, all of which have been linked to bronchiectasis." (PMID 41149860, 2025). "Bronchiectasis, GGO and fibrotic ILD were associated with low IgA levels, whereas high CD4+ T cells percentage was related to GGO." (PMID 37548814, 2023). "Further multivariate analysis showed that CD4/CD8 ratio (OR 1.409, 95% CI 1.045–1.901, p = 0.0254) is likely to be an independent risk factor for bronchiectasis patients complicated with pulmonary embolism." (PMID 35681174, 2022). "For 43 bronchiectasis patients, the mean ± standard deviation percentage of eosinophils, neutrophils, CD4+ T cells and CD8+ T cells was 8.3 ± 5.9, 9.8 ± 5.0, 33.1 ± 9.7, and 15.8 ± 7.5, respectively." (PMID 32154248, 2020). "The CD4/CD8 ratio was significantly higher in patients with bronchiectasis than in controls (3.08 ± 2.05 vs 1.68 ± 0.78; p = 0.002)." (PMID 17224076, 2007). "A predominant CD4+ T cell infiltrate in the bronchial mucosa in bronchiectasis patients has been observed." (PMID 17224076, 2007). "This study on BAL fluid has also shown that the CD4/CD8 ratio is significantly increased in patients with bronchiectasis." (PMID 17224076, 2007). "Analysis of T-lymphocyte subsets in BAL fluid indicates that, in patients with bronchiectasis due to mustard gas exposed, both the percentage and total numbers of CD4 T cells increase and the percentage of CD8 T cells decreases." (PMID 17224076, 2007). "In conclusion, CD4 T cells in BAL fluid were significantly elevated in patients with bronchiectasis." (PMID 17224076, 2007). "This study was designed to analyze bronchoalveolar lavage lymphocyte subsets and to determine the ratio of CD4 to CD8 lymphocytes in BAL fluid in these veterans with bronchiectasis." (PMID 17224076, 2007). "A significant positive correlation was observed between the HRCT scores and both the percentage and the absolute number of CD4 lymphocytes in BAL fluid in patients with bronchiectasis (r = -0.49, p = 0.009; r = -0.50, p = 0.008; respectively)." (PMID 17224076, 2007). "A significant correlation was observed between the HRCT scores and both the percentage and the absolute number of CD4 lymphocytes in BAL fluid in patients with bronchiectasis (r = -0.49, p = 0.009; r = -0.50, p = 0.008; respectively)." (PMID 17224076, 2007). "Notably, CD4+ T‐cell counts in both groups in our study were already below the normal adult reference range, indicating a baseline immune deficit in this elderly bronchiectasis population." (PMID 41448851, 2025). "We speculate that the increased CD4/CD8 ratio may be related to the activated immune and inflammatory state in BE/PE patients and the occurrence of pulmonary embolism may change the original CD4/CD8 ratio in patients with bronchiectasis." (PMID 35681174, 2022). "Consequently, the CD4/CD8 ratio was significantly higher in patients with bronchiectasis than in healthy controls (3.08 ± 2.05 versus 1.68 ± 0.78; p = 0.002)." (PMID 17224076, 2007).
bronchiectasis (continued). "CD4 lymphocytes expressed as percentage or absolute number were significantly higher in patients with bronchiectasis than in controls (32.17 ± 16.00 vs 23.40 ± 6.97%, respectively; p = 0.01; and 3.31 ± 2.03 vs 1.88 ± 0.83 × 103 cells/ml, respectively; p = 0.001)." (PMID 17224076, 2007). "Recurrent URTI and LRTI, bronchiectasis, Addison’s disease, dysgammaglobulinemia, ↓CD19+ B cells, inverted CD4/CD8 ratio, ↑CD8+CD45RA+CD27- TEMRA cells, abnormal CD4+CD45RA/RO ratio." (PMID 41583441, 2025). "CD8+, CD4+, and regulatory T cells counts were higher in NTM-PD than in bronchiectasis." (PMID 39138424, 2024). "However, the stimuli and the mechanisms that mediate CD4 T-cell recruitment to the lung of our patients with bronchiectasis are not understood." (PMID 17224076, 2007). "Furthermore, CVID patients with bronchiectasis have significantly lower IgA and IgM serum levels, lower total B cell and switched memory B cell numbers, expanded CD21lo immature B cells, as well as fewer T CD4+ cells than those without bronchiectasis." (PMID 40141295, 2025).
IgG4-related disease (21 papers, 2011 to 2026). "As CD4+ CTLs were implicated in several immune-mediated fibroinflammatory diseases, such as IgG4-related disease and systematic sclerosis, rapamycin is a promising potential intervention for GO, especially to prevent and/or avoid fibrotic complications." (PMID 36580373, 2023). "These CD4+CTLs also play a critical role in IgG4-related disease (IgG4-RD), which has an unknown cause and is characterized by highly fibrotic lesions, with dense lymphoplasmacytic infiltrates containing a preponderance of IgG4-expressing plasma cells." (PMID 41009359, 2025). "It has been speculated that T cells are associated with pathogenesis, because many CD4 T cells are seen at sites of inflammation in IgG4-related disease." (PMID 27156948, 2016). "scRNA-seq analysis of blood lymphocytes from patients with IgG4-related disease revealed the presence of not only CD4+ CTLs but also CD4+ T cells expressing ISGs48." (PMID 40393992, 2025). "In IgG4-related disease, presumably self-reactive cytotoxic CD4 T cells infiltrate tissues, are reactivated by T cells and induce apoptotic death." (PMID 34539675, 2021). "IgG4-related disease (IgG4-RD) is a novel clinical entity characterized by tumefactive lesions, lymphoplasmacytic infiltrates consisting of CD4+ T cells and numerous IgG4+ plasma cells, and tissue fibrosis." (PMID 32487061, 2020). "It has been observed that CD4 T cells are present at the sites of inflammation in IgG4-related disease." (PMID 28299186, 2017). "To clarify the role of Tregs in IgG4-related diseases, we analyzed Tregs showing CD4+CD25high and CD4+CD25+CD45RA+ (naïve) from peripheral blood by flow cytometry in the patients with Type 1 AIP." (PMID 22536257, 2012). "This new research is exciting, as CD4-positive CTLs may ultimately prove to be the major mechanism of pathogenesis of IgG4-related disease." (PMID 28299186, 2017). "Finally, rituximab-mediated B-cell depletion results in both clinical improvement of patients’ IgG4-related disease and a decrease in the number of CD4-positive CTLs64." (PMID 28299186, 2017). "In view of the results from animal models, even though CD8+ T cells may be partially involved, CD4+ T cells play major roles in the development of systemic inflammation, which are similar to the lesions in human IgG4-related diseases." (PMID 22536257, 2012). "Follicular helper CD4+ T (Tfh) cells have a critical role in IgG4 production by B cells in IgG4-related disease (IgG4-RD)." (PMID 32487061, 2020). "CD4+ T cells play critical roles in the pathogenesis of IgG4-related disease (IgG4-RD)." (PMID 31856905, 2019). "Interestingly, CD4+ CTLs with an effector/memory phenotype were expanded in inflamed tissue sites and secreted the profibrotic cytokine IFNG in IgG4-related disease." (PMID 36580373, 2023). "Future research is needed to ascertain whether there is any interaction between CD4-positive CTL or Th2 Tfh cells and M2 macrophages in promoting IgG4-related disease." (PMID 28299186, 2017). "Currently, fibrosis of IgG4-related disease is thought to be induced by profibrotic cytokines such as transforming growth factor beta 1 (TGFB1), interleukin 1 beta (IL1B) and interferon gamma (IFNG), which are secreted by regulatory T cells (Tregs) and CD4-positive cytotoxic T cells." (PMID 29439708, 2018). "The activation of Treg cells in IgG4-related disease is suggested by the high expression of the forkhead box P3 (FOXP3) mRNA in tissue by the infiltrates of CD4+CD25+ Treg cells at affected sites and by the increased number of CD4+CD25+ Treg cells in the blood." (PMID 26491451, 2015).
immune thrombocytopenia (21 papers, 2018 to 2026). "Primary immune thrombocytopenia involves antibody-driven platelet loss and perturbed CD4+ T cell regulation." (PMID 41244589, 2025). "The pathogenesis of immune thrombocytopenia can be traced to imbalanced Th1 and Th2 subsets of CD4+ T cells." (PMID 36285187, 2022). "Expression of MEG3 has been shown to be elevated in CD4 + T cells of patients with immune thrombocytopenic purpura." (PMID 34373511, 2021). "The CD16+ monocyte subset was positively correlated with IFN− CD4+ T cells, but negatively correlated with CD4+CD25hiFoxp3+ Treg cells in immune thrombocytopenia." (PMID 31651258, 2019). "MEG3 expression is upregulated in CD4+ T cells of patients with immune thrombocytopenic purpura and this enhances the immune imbalance of Treg/Th1723." (PMID 31729423, 2019). "MEG3, a lncRNA expressed in CD4+ T cells, contributes to the imbalance of Tregs/Th17 ratio in patients with immune thrombocytopenic purpura." (PMID 30319599, 2018). "Additionally, the overexpressed lncRNA MEG3 interacted with miR-125a-5p and suppressed its expression, whereas the downregulation of MEG3 increased the expression of FOXP3 via miR-125a-5p in the CD4+ T cells in immune thrombocytopenic purpura." (PMID 37709486, 2023). "Disequilibrium of CD4+ T-cell subpopulations in peripheral blood (PB) of patients with primary immune thrombocytopenia (ITP) has been well established, whereas the profile of CD4+ T-cell subpopulations in bone marrow (BM) remains elusive." (PMID 31853219, 2019). "In immune thrombocytopenia, increased WRS expression in CD4+ and CD8+ T cells may enhance survival of autoreactive T cells." (PMID 32933162, 2020).